REG1CP (regenerating family member 1 gamma, pseudogene)
Synonyms: RS; formerly REGL; REG1P
Gene: Transcribed unprocessed pseudogene on chromosome 2 (79,135,701 to 79,138,030, reverse strand). Ensembl gene ENSG00000204787.
Diseases named in the same sentence as REG1CP in open-access papers:
REG1CP is named in the same sentence as 12 diseases in open-access papers, as found by Europe PMC text mining. Sharing a sentence is not in itself a finding about the gene and the disease. The quoted sentences say what the papers report.
colorectal cancer (3 papers, 2019 to 2025). A primary or metastatic malignant neoplasm that affects the colon or rectum. "REG1CP is notably upregulated in both preneoplastic colonic lesions and colorectal carcinomas, suggesting a cooperative axis between REG1CP and REG3A in promoting colorectal tumorigenesis." (PMID 40723277, 2025). "Reg1cp belongs to Reg family and has been reported to promote colorectal cancer cell proliferation through activation of REG3A in colon cells." (PMID 36302749, 2022). "Consistently, analysis of clinical colorectal cancer (CRC) data obtained from the TCGA showed that patients with colon cancers expressing higher levels of REG1CP had worse PFS." (PMID 31767869, 2019).
colon adenoma (2 papers, 2019 to 2021). An adenoma that arises from the colon. "In contrast, REP1CP levels appeared higher in colon adenomas and dysplastic colon mucosa compared with paired normal mucosa, proposing that upregulation of REG1CP is an early event during colorectal tumorigenesis." (PMID 31767869, 2019). "Moreover, no significant changes were found between REG1CP expression in colon cancer vs. colon adenoma." (PMID 31767869, 2019).
colon cancer (2 papers, 2019 to 2021). "The results revealed that REG1CP was the most prominently upregulated lncRNAs in colon cancer cells." (PMID 31767869, 2019). "We next analysed the relationship between REG1CP expression, colon cancer development and progression." (PMID 31767869, 2019). "Indeed, shRNA silencing of REG1CP reduced REG3A expression at both the transcript and protein levels in LIM1215 and HT-29 colon cancer cells that expressed relatively high levels of REG1CP among a panel of colon cancer cell lines." (PMID 31767869, 2019). "Moreover, qPCR analysis of two independent cohorts (cohort 1 & 2) of formalin-fixed paraffin-embedded (FFPE) colon cancer tissues in comparison with paired normal mucosa also showed that REG1CP was upregulated in the majority of colon cancers." (PMID 31767869, 2019). "Indeed, absolute quantitation using digital droplet PCR (ddPCR) demonstrated that there were ~80 and ~100 REG1CP molecules per HT-29 and LIM1215 colon cancer cell, respectively, compared with ~15 REG1CP molecules per normal colon epithelial (FHC) cell." (PMID 31767869, 2019).
diabetes (1 paper, 2022). "These Reg1cp+/mut and Reg1cpmut/mut individuals had higher incidence of diabetes and prediabetic states compared with those with the WT gene." (PMID 36302749, 2022).
Impaired glucose tolerance (1 paper, 2022). An abnormal resistance to glucose, i.e., a reduction in the ability to maintain glucose levels in the blood stream within normal limits following oral or intravenous administration of glucose. "After 12-week HFD started at 12 weeks of age, we found that the impaired glucose tolerance as judged by GTTs and deteriorated insulin resistance as detected by ITTs induced by HFD were aggravated in Reg1cp-mutRIP+ mice compared with their littermate controls." (PMID 36302749, 2022).
Insulin resistance (1 paper, 2022). Increased resistance towards insulin, that is, diminished effectiveness of insulin in reducing blood glucose levels. "In the present study, we demonstrate this mutation in Reg1cp promotes T2D development both by impaired islet β cell function and increased insulin resistance." (PMID 36302749, 2022). "In the current study, we identified a mutation in Reg1cp and presented genetic, clinical, in vivo and in vitro experimental evidences to demonstrate that Reg1cp promotes the development of T2D both by impairing islet β cell function and increasing insulin resistance." (PMID 36302749, 2022). "Thus, the higher circulation level of CHGA in Reg1cp-mutRIP+ mice might be cause by the hormone imbalance induced by insulin resistance." (PMID 36302749, 2022). "Mice with islet β cell specific Mut-Reg1cp knock-in have more severe β cell dysfunction and insulin resistance." (PMID 36302749, 2022). "We found that Mut-Reg1cp in islet β cells not only impaired β cell function, but also aggravated insulin resistance in mice." (PMID 36302749, 2022). "Furthermore, islet derived exosomes transfer Mut-Reg1cp into peripheral tissue, which then promote insulin resistance by inhibiting AdipoR1 translation and adiponectin signaling." (PMID 36302749, 2022). "To further investigate the potential reasons for the significant increased insulin resistance in Reg1cp-mutRIP+ mice, we analyzed circulating proteins in serum from Reg1cp-wtRIP+ mice, Reg1cp-mutRIP+ mice and wild type mice after 12-week HFD through mass spectrometry." (PMID 36302749, 2022). "Reg1cp-mutRIP+ mice showed significant increasing insulin resistance indicated by ITTs." (PMID 36302749, 2022).
cancer (1 paper, 2019). A tumor composed of atypical neoplastic, often pleomorphic cells that invade other tissues. "As such, REG1CP promotes cancer cell proliferation and tumorigenicity and its upregulation is associated with poor outcome of patients." (PMID 31767869, 2019). "Moreover, we demonstrate the functional importance of this mechanism, showing that REG1CP promotes cancer cell proliferation and tumorigenicity through activation of REG3A." (PMID 31767869, 2019). "Moreover, overexpression of REG3A reversed the reduction in growth of LIM1215-shREG1CP xenografts in nu/nu mice treated with Dox, consistent with the notion that REG1CP functions through REG3A to sustain cancer cell proliferation in vivo." (PMID 31767869, 2019).
REG1CP also shares sentences with these, for which no sentence is quoted: tumor (2 papers); nasopharyngeal carcinoma (1); osteosarcoma (1); prostate carcinoma (1); type 2 diabetes (1).